SIRT3 (sirtuin 3)
Diseases named in the same sentence as SIRT3 in open-access papers (continued):
Sharing a sentence is not in itself a finding about the gene and the disease.
endothelial dysfunction (continued). "Furthermore, previous studies found a series of activator of SIRT3, such as resveratrol and melatonin, ameliorate endothelial dysfunction." (PMID 34180125, 2021). "In addition, we would like to point out that endothelial dysfunction in Sirt3−/− mice was observed only upon exposure to a high-cholesterol diet, known to induce oxidative stress." (PMID 27071400, 2016). "However, it is unclear whether sirtuins, such as SIRT3 in ECs, which have a known role against endothelial dysfunction and vascular inflammation, are required for the beneficial effect of NAD+ in endothelial cells and atherosclerosis." (PMID 35453391, 2022). "Furthermore, inhibition of p300 acetyltransferase activity with C646 significantly reduces the SIRT3 deficiency-induced elevated levels of inflammatory factors NF-kB and VCAM1 in myocardial tissues, increases the levels of eNOS and ameliorates endothelial dysfunction." (PMID 34831061, 2021). "SIRT3 siRNA could worsen AngII induced endothelial dysfunction via increase generation of ROS." (PMID 26223796, 2015). "Downregulation of SIRT3 increases mtROS generation, accompanied by reduction of NO release and activation of NLRP3 inflammasome, whereas activation of SIRT3 by honokiol inactivates the NLRP3 pathway, thereby preventing endothelial dysfunction." (PMID 41323268, 2025). "Sirt3-AMPK signaling is also important for suppressing vascular inflammation and endothelial dysfunction during early sepsis." (PMID 35729330, 2022). "The proposed mechanism states that SIRT3 deacetylates and activates SOD2, which protects against endothelial dysfunction and HT." (PMID 34829803, 2021). "In our study, ALA supplementation rescued SIRT3 reduction and SOD2 hyperacetylation, improved endothelial dysfunction and reduced blood pressure elevation in hypertensive animals." (PMID 32015327, 2020). "Taken together, these results suggest that SIRT3 is a positive regulator in endothelial insulin sensitivity and a protector against HFD-induced endothelial dysfunction." (PMID 27000941, 2016). "On the basis of the anti-inflammatory and antioxidant effects of NAD+ on ECs, which are independent of SIRT3, we next explored whether NAD+ alleviates vascular endothelial dysfunction in a similar manner because oxidative stress is closely associated with endothelial dysfunction." (PMID 35453391, 2022).
type 2 diabetes (42 papers, 2009 to 2025). "SIRT3 is associated with the development of atherosclerosis among individuals with type 2 diabetes via upregulating eNOS and PPAR-α." (PMID 41567643, 2025). "SIRT3 has been associated with the advancement of atherosclerosis in individuals with type 2 diabetes by raising PPAR-α and eNOS levels while lowering iNOS levels." (PMID 41567643, 2025). "Recent studies highlight that expression and activity of SIRT3 are decreased in type 2 diabetes, which is associated with defects in glucose tolerance." (PMID 31093315, 2019). "Allof this work will be important as we fight against aging and associateddisorders ranging from type 2 diabetes (and other metabolic diseases) to breastcancer, in which expression of SIRT3 is aberrant." (PMID 20157566, 2009). "In type 2 diabetic mice, retinal dysfunction may be related to the loss of SIRT3 and SIRT5 because SIRT3 may promote autophagy by downregulating the expression of angiogenesis-related genes in retinal endothelial cells." (PMID 36510610, 2022). "We have previously reported that mitochondrial oxidative stress is induced by decreased superoxide dismutase 2 (SOD2) and isocitrate dehydrogenase 2 (IDH2) activities associated with a reduced intracellular NAD+/NADH ratio and Sirt3 activity in the kidneys of type 2 diabetic rats." (PMID 32507768, 2020). "Several studies have described pharmacological approaches leading to SIRT3 activation, for the treatment of diseases associated with SIRT3 deficiency and several aging-related conditions, such as type 2 diabetes, most persistent diseases of rheumatologic interest or chronic lymphocytic leukemia." (PMID 33182469, 2020). "The NAD+-dependent protein deacetylase Sirtuin-3 (SIRT3) has been implicated in Type 2 diabetes." (PMID 25915406, 2015). "In conclusion, our study demonstrates that CD38 deficiency improved type 2 diabetes-induced cardiomyopathy via inhibiting pyroptosis and apoptosis in vivo and in vitro, in which the underlying mechanisms were mainly related to activating Sirt3/FOXO3a signaling pathways." (PMID 37958991, 2023). "Indeed, maternal low protein (8%) and postnatal high diets (45%) in the rats have been shown to increase the risk of type II diabetes by decreasing skeletal muscle oxidative respiration, via increased sirtuin 3 (Sirt3), and potentially by decreasing the activity of succinate dehydrogenase (SDH)." (PMID 27102569, 2016). "In a murine model of type 2 diabetes, upregulation of Sirt3 has been shown to increase motor nerve conduction velocity and alleviate hyperglycemia‐induced sciatic nerve inflammation." (PMID 39123294, 2024). "We hope that our findings elucidate the molecular mechanism of Sirt3 modulators in regulating insulin signaling pathway and highlight the therapeutic potential of Sirt3 activator in the treatment of type 2 diabetes and metabolic diseases." (PMID 35409099, 2022). "Metformin, a drug used in type 2 diabetes, can increase SIRT3 expression in peripheral blood leukocytes of type 2 diabetes patients and low mitochondria ROS." (PMID 35054829, 2022). "Here, we show for the first time that CD38 plays a crucial role in mitochondrial oxidative stress by reducing the NAD+/NADH ratio and Sirt3 activity in the kidneys of type 2 diabetic rats." (PMID 32507768, 2020). "Sirt3 has an important role in regulation of metabolic pathways and metabolic diseases such as type 2 diabetes, cancer, and cardiovascular diseases." (PMID 33191653, 2020). "Downregulated expression of SIRT3 has been observed in the isolated islets from patients with type 2 diabetes." (PMID 32722262, 2020). "Only a little has been reported for the role of SIRT3 in pancreatic β cells, and the evidence supporting the importance of SIRT3 in pancreatic islet β cells related to Type 2 diabetes can be summarized as follows." (PMID 25915406, 2015). "SIRT1 regulate insulin secretion in pancreatic β cells and SIRT3 is suppressed in pancreatic islets isolated from human type 2 diabetic patients." (PMID 24073959, 2013).
type 2 diabetes (continued). "Although a previous study suggested that SIRT3 signaling may be involved in rats with lung I/R injury and type II diabetes, the detailed mechanisms, as well as whether PKM2 functions as an antiapoptotic substrate of SIRT3, require further investigation." (PMID 35821123, 2022). "Sirtuin-3 (Sirt3) is a major mitochondrial deacetylase enzyme that regulates multiple metabolic pathways, and its expression is decreased in diabetes type 1 and type 2 diabetes." (PMID 35409099, 2022). "Sirt3 expression was markedly decreased in islets of patients with type 2 diabetes." (PMID 35386849, 2022). "Additionally, 50 and 100mg/kg of QUR can improve the expression of sirtuin-3 (SIRT3) in type 2 diabetic mice and reduce the levels of nitric oxide (NO) and ROS, thereby reducing the oxidative stress response and preventing the apoptosis of pancreatic β cells." (PMID 35889348, 2022). "SIRT3 levels are lower in pancreatic islets in human patients afflicted with Type 2 diabetes." (PMID 25915406, 2015). "We find that DNA variation in the Sirt3 promoter may contribute to impaired glucose homeostasis in the GK model of type 2 diabetes." (PMID 24743600, 2014). "In this study, we discovered that the reduction in Sirt3 activity was involved inrenal mitochondrial oxidative stress through a decrease in the activity ofanti-oxidative enzymes via increased acetylation levels of those enzymes in thekidney of type 2 diabetic animal model, ZDFRs." (PMID 29897845, 2018). "Another study demonstrated that Que can regulate the SIRT3 protein to improve the levels of SOD2 and CAT in type 2 diabetes (T2DM) mice." (PMID 38675511, 2024). "This study investigated the effects of type 1 diabetes (T1D), type 2 diabetes (T2D), and HT on the expression levels of SIRT1, SIRT3, and manganese superoxide dismutase (SOD2)." (PMID 30736780, 2019). "Treatment with the iSGLT2 dapagliflozin reduced DPP4 serum levels in patients with type 2 diabetes and non-alcoholic fatty liver disease, while the DPP4 inhibitor sitagliptin ameliorated the ischemia/reperfusion-induced injury in cardiomyocytes by mediating SIRT3 upregulation and autophagy." (PMID 38811901, 2024).
atherosclerosis (41 papers, 2011 to 2025). A disease characterized by the build-up of fatty material and calcium deposition in the arterial wall resulting in partial or complete occlusion of the arterial lumen. "Up-regulation of SIRT3 can attenuate endothelial cellular senescence to decrease the risk of atherosclerosis." (PMID 32724473, 2020). "We therefore investigated the role of Sirt3 in atherogenesis and energy expenditure using a loss-of-function approach in a mouse model of atherosclerosis." (PMID 24370889, 2014). "We aimed to investigate whether Sirt3 deficiency affects atherosclerosis, plaque vulnerability, and metabolic homeostasis." (PMID 24370889, 2014). "This indicates a functional link between SIRT3 activity and host-microbiome interactions in atherosclerosis." (PMID 40860195, 2025). "To validate the potential role of the SIRT3/SOD2 pathway in Micu1-regulated atherosclerosis, we analyzed SIRT3 expression and levels of acetylated SOD2 in aortic root sections of hypercholesterolemic Micu1ECKO and Micu1fl/fl mice." (PMID 40166941, 2025). "In summary, our study has provided new insights into the role of endothelial SIRT3 in maintaining vascular homeostasis and preventing atherosclerosis through SIRT3‐mediated deacetylation of ASS1, which is responsible for de novo arginine biosynthesis." (PMID 38233193, 2024). "This study provides compelling evidence supporting the protective role of endothelial SIRT3 in atherosclerosis and also suggests a critical role of SIRT3‐induced deacetylation of ASS1 by ECs for arginine synthesis." (PMID 38233193, 2024). "The present study aims to study the role and mechanism of SIRT3 in EC function during atherosclerosis." (PMID 38233193, 2024). "Without SIRT3, impaired ASS1 activity and L‐arginine deficiency are critical factors contributing to mitochondrial dysfunction, disturbance of NO and redox status, endothelial inflammation, and enhanced atherosclerosis induced by SIRT3 deletion in mice." (PMID 38233193, 2024). "Regarding the effect of SIRT3 expression on atherosclerosis, SIRT3 downregulation was observed within the atherosclerotic plaques of vascular tissue from mice and in the aortas of atherosclerotic rats." (PMID 35453391, 2022). "The investigators found that SIRT3 expression was downregulated in the aorta of rats with atherosclerosis and closely related to apoptosis." (PMID 35677446, 2022). "For example, melatonin induces SIRT3 activation in atherosclerotic plaques to ameliorate the progression of atherosclerosis." (PMID 35453391, 2022). "Further investigation into the nature of this interaction is needed, especially regarding final SIRT3 effects relevant in atherosclerosis, such as: ROS generation, NLRP3-mediated inflammation, apoptosis and cellular reaction to stress." (PMID 33499277, 2021). "The direct interaction between profilin and SIRT-3 seems to be particularly promising in shedding new light on the pathogenesis of atherosclerosis." (PMID 33499277, 2021). "In STZ-diabetic mice, acacetin significantly upregulated the decreased signaling molecules (i.e. SOD, Bcl-2, PGC-1α, pAMPK, Sirt3 and Sirt1) in aorta tissue and attenuated atherosclerosis." (PMID 33519472, 2020). "Recent study has shown that knockout of SIRT3 enhances weight gain and reduces rapid metabolic adaptation in LDL receptor KO mice, implicating a critical role of SIRT3 in delaying the development of atherosclerosis." (PMID 30873415, 2019). "The findings suggest that Volvalerenic A, the primary metabolite in KYXC, can enhance the accumulation of lipids, mitigate the inflammatory milieu, alleviate mitochondrial damage, and eventually impede the progression of atherosclerosis by activating the PGC-1α/Sirt3/Epac1 signaling pathway." (PMID 39629078, 2024).
atherosclerosis (continued). "Wild‐type Sirt3f/f mice and endothelium‐selective SIRT3 knockout Sirt3f/f; Cdh5Cre/+ (Sirt3EC‐KO) mice are injected with adeno‐associated virus (AAV) to overexpress PCSK9 and fed with high‐cholesterol diet (HCD) for 12 weeks to induce atherosclerosis." (PMID 38233193, 2024). "In addition, melatonin has been reported to prevent atherosclerosis progression by attenuating NLRP3 inflammasome activation by activating autophagy through the Sirt3/FOXO3a/Parkin signaling pathway." (PMID 37570258, 2023). "In line with this, several histone demethylases or histone methyl transferases have been identified such as sirtuin 3 (SIRT3) and lysine-specific demethylase 7 homolog 3 (JMJD3) and associated with atherosclerosis development pathways including inflammation and endothelial functioning." (PMID 35563540, 2022). "Importantly, HIF-1α is highly expressed in smooth muscle cells and cardiomyocytes, which underscore the potential role of a possible profilin-SIRT3-HIF-1α axis in atherosclerosis." (PMID 33499277, 2021). "SIRT3 seems to have several protective roles in the pathogenesis of atherosclerosis." (PMID 33499277, 2021). "Taking into consideration the importance of apoptosis in thromboembolic complications of atherosclerosis, SIRT3 may be one of the most important proteins protecting against MI and stroke." (PMID 33499277, 2021). "This was partially also mediated via an increased level of free radicals (peroxynitrite), suggesting another way in which SIRT3-profilin interplay could influence atherosclerosis." (PMID 33499277, 2021). "SIRT3 also has important metabolic functions with implications for atherosclerosis." (PMID 33499277, 2021). "Interestingly, a hormone named Melatonin, which targets the melatonin receptor to play a role in sleep, now has been found to be a SIRT3 activator that plays a protective role in heart disease 183, liver injury 184 and atherosclerosis." (PMID 32724473, 2020). "Additionally, in a mouse model of atherosclerosis, melatonin activates SIRT3-FOXO3a-Parkin regulated mitophagy to prevent inflammation and atherosclerotic progression." (PMID 32724473, 2020). "In addition, overexpressed SIRT3 enhances autophagy, which plays an important role in the development of cardiovascular diseases, including atherosclerosis, cardiac ischemia/reperfusion, cardiomyopathy and heart failure." (PMID 27078640, 2016). "Thus, we hypothesize that MICU1 regulates vascular inflammation and atherosclerosis potentially through the SIRT3/SOD2/mROS pathway." (PMID 40166941, 2025). "However, the role of SIRT3 in myeloid cells or other immune cells in the context of atherosclerosis remains largely unknown." (PMID 38233193, 2024). "However, the specific role of endothelial SIRT3 during atherosclerosis remains poorly understood." (PMID 38233193, 2024). "Therefore, the role of SIRT3 in atherosclerosis remains to be elucidated." (PMID 29643974, 2018). "Indeed, SIRT3 deficiency did not affect endothelial activation, plaque macrophage and T cell infiltration and atherosclerosis in low-density lipoprotein receptor knockout mice." (PMID 28634345, 2017). "To date, the role of Sirt3 in vascular biology and specifically in atherosclerosis remains unknown." (PMID 24370889, 2014). "However, the role of Sirt3 in atherosclerosis remains enigmatic." (PMID 24370889, 2014). "In this study, we demonstrated the role of MICU1 in regulating SIRT3/SOD2 activity in the context of vascular inflammation and atherosclerosis." (PMID 40166941, 2025). "This investigation delves into the role of Sirtuin 3 (SIRT3), a mitochondrial deacetylase, within endothelial cells during atherosclerosis." (PMID 38233193, 2024).
atherosclerosis (continued). "Idebenone, which is a compound similar to co-enzyme Q10, also increases SIRT3 activity and further activates SOD2, which suppresses ROS to ameliorate atherosclerosis in ApoE−/− mice." (PMID 35453391, 2022). "Melatonin has also been shown to hinder the progression of atherosclerosis by mediating NLRP3 inflammasome activation and SIRT3 activity." (PMID 34292876, 2021). "Moreover, TMAO may have a direct influence on cardiac oxidative stress, but it stimulated mitochondrial ROS generation and inhibited manganese superoxide dismutase 2 (SOD2) activation and sirtuin 3 (SIRT3) expressions in HUVECs and aortas in apolipoprotein E (ApoE)-KO mice with atherosclerosis." (PMID 34201938, 2021). "Melatonin has been demonstrated to ameliorate atherosclerosis by inhibiting NLRP3 inflammasome, which is regulated by SIRT3/FOXO3/Parkin signaling." (PMID 35004893, 2021). "For example, overexpression of SIRT3 can deacetylate and activate superoxide dismutase 2 (SOD2) to reduce intracellular reactive oxygen species (ROS), which in turn improves atherosclerosis." (PMID 32139662, 2020). "Therefore, decreased SIRT3 levels may contribute to MI development by: 1) affecting lipid metabolism, inflammation and other pathways, initiating the atherosclerosis; and 2) interfering with fatty acid oxidation, ROS generation and mitochondrial functions, leading to death of cardiomyocytes." (PMID 27078640, 2016). "Therefore, using the endothelium selective Sirt3 knockout mice, we performed a more comprehensive study on the detailed role of SIRT3 in EC function during atherosclerosis and demonstrated that ASS1‐dependent arginine biosynthesis as a target of SIRT3 in EC." (PMID 38233193, 2024). "Moreover, SIRT3 and SIRT6 have been shown to play significant roles in protecting the vasculature against atherosclerosis." (PMID 35677446, 2022). "In the case of melatonin, a neurohormone produced by the pineal gland, it has been observed that SIRT3 activity rises without increasing its expression in an atherosclerosis mouse model or in cadmium-exposed HepG2 cells." (PMID 35054829, 2022). "This may interact with the SIRT3 and SIRT5, which are mitochondrial SIRTs, in controlling ROS production and therefore the development of atherosclerosis." (PMID 22087257, 2011). "The present study tested whether endothelial-selective SIRT3 deletion accelerates vascular inflammation and oxidative stress, and assessed the protective effect of NAD+ to alleviate these changes in endothelial cells and in mouse models of atherosclerosis." (PMID 35453391, 2022). "Moreover, a putative effect of Sirt3 on early atherosclerosis or vascular function was not assessed." (PMID 24370889, 2014). "In absence of an antioxidative effect within the vessel wall, and given the lack of an effect of Sirt3 deletion on atherosclerosis, the increase in systemic oxidative stress appears unlikely to affect vascular inflammation and atherosclerotic burden in the context of advanced atherosclerosis." (PMID 24370889, 2014). "Our results support the SIRT3-dependent and -independent of NAD+ to improve endothelial function in atherosclerosis." (PMID 35453391, 2022). "Studies investigating mice lacking SIRT3 have been shown to have decreased levels of fatty acid oxidation compared to wild-type mice, possibly an important factor in high LDL levels that help progress to atherosclerosis." (PMID 38333571, 2024).